NPM1 (nucleophosmin 1)
Diseases named in the same sentence as NPM1 in open-access papers (continued):
Sharing a sentence is not in itself a finding about the gene and the disease.
infection (32 papers, 2007 to 2026). The state of being infected such as from the introduction of a foreign agent such as serum, vaccine, antigenic substance or organism. "NPM1 shuttles between the nucleus and the cytoplasm and has been implicated in infection with multiple viruses." (PMID 37409962, 2023). "Of the 4 patients with an isolated NPM1 mutation, 2 patients that were treated for molecular relapse achieved CR MRDneg, 1 died of infection before first response evaluation and 1 progressed." (PMID 33191481, 2021). "The viral core protein has been shown to co-localize with nucleolar protein nucleophosmin (NPM1) and cause its redistribution during infection suggesting a possible role in the intracellular localization of the core protein and replication of JEV." (PMID 24599148, 2014). "Based on site-directed mutagenesis and coimmunoprecipitation studies, it was also observed that amino acid residues N24 and Y114 of the CHIKV nsP3 macrodomain, known to be involved in virus virulence, bind ADP-ribosylated NPM1 to inhibit infection." (PMID 37409962, 2023). "In accordance with infection efficiencies, Western blot analysis evidenced a clear downregulation of NPM1 protein levels." (PMID 34356831, 2021). "The results showed that the expression of PCV2 Cap and Rep was markedly increased in NPM1-silenced cells transfected with mNPM1 during infection compared with cells transfected with empty vector." (PMID 33073687, 2020). "In order to further verify that TBEV did not induce nucleolar re-arrangement due to nucleolar stress, we analysed the nucleolar structure upon TBEV Hypr infection using nucleophosmin (NPM1; a nucleolar marker)." (PMID 31560682, 2019). "The stable DKO MEF cell lines were created through infection with retroviruses carrying the Thy1.1 cell surface marker in frame with an internal ribosomal entry site (IRES) and an mCherry-NPM1 variant gene." (PMID 26836305, 2016). "To determine whether the localization of NPM1 changes during infection, we analyzed the kinetics of NPM1 localization during infection and analyzed the levels of NPM1 in nuclear and cytoplasmic compartments." (PMID 37409962, 2023). "Moreover, infection with PCV3 was found to upregulate the expression of NPM1 in cultured PK15 cells, while the expression of Cap protein induced NPM1 redistribution from the nucleus to the cytoplasm." (PMID 34113334, 2021). "Furthermore, infection with PCV3 was found to upregulate the expression of NPM1 in cultured cells, and the expression of Cap protein induced the redistribution of NPM1 from the nucleus to the cytoplasm." (PMID 34113334, 2021). "To enable fast and efficient recombination, we established a toolbox for the retroviral infection of murine cells with Cas9 and sgRNAs targeting the genes Npm1 and Alk, in which infection efficacy could be monitored through flow cytometric analysis of linked fluorescent markers." (PMID 40647524, 2025). "In this study, infection with the OROV MD023 strain led to nuclear accumulation of NSs and redistribution of nucleophosmin 1 (NPM1) from the nucleolus." (PMID 40928251, 2025). "The results showed that the levels of NPM1 protein expression and mRNA transcription increased significantly in PCV3-infected PK15 cells at 48, 72, and 96 h post-infection." (PMID 34113334, 2021). "NPM1 is known to interact with HIV-1 Tat, and infection with HIV-1 induces acetylation of NPM1." (PMID 38203551, 2023). "Infection with MR766- but not PRV increased fraction of a-nucleolar cells with most NPM1 translocated to the nucleoplasm and lack of a clearly identifiable nucleolus." (PMID 29192272, 2017). "We observed that NPM1 binds CHIKV nonstructural protein 3 (nsP3) strongly via its macrodomain, thereby exerting a direct interaction with viral proteins to limit infection." (PMID 37409962, 2023). "Western blot analysis showed a higher intensity lane of Cap in NPM1-GFP expressing cells than in GFP-expressing cells and no-transduced cells at 72–96 h after PCV3 infection." (PMID 34113334, 2021).
infection (continued). "The copy numbers of viral DNA in the NPM1 overexpressed cells were higher than those in the GFP overexpressing cells and no-transduced cells at 72–96 h post-infection." (PMID 34113334, 2021). "After 9 days of LV infection, roughly 50% of transduced HPB-ALL cells were GFP-positive, irrespective of the condition, suggesting that decreased B23/NPM1 expression did not negatively impact T-ALL cell fitness." (PMID 32471246, 2020). "The downregulation of nucleophosmin 1 (C-7), which can not be detected in cells infected with active VACV IHD-W, suggests that it is a cellular response to the infection for the purpose of anti-viral defence." (PMID 21806805, 2011).
hematological malignancies (18 papers, 2009 to 2026). "The fact that NPM1 is frequently mutated, rearranged, and overexpressed in hematological disorders has led investigators to propose that NPM1 could be a proto-oncogene." (PMID 23271972, 2012). "The NPM1 gene bears frequent mutations in hematological diseases, especially in AML, with approximately 30% of patients harbouring a frameshift mutation resulting in aberrant NPM1 cytoplasmic localisation (NPMc+)." (PMID 34842767, 2021). "Deletions and chromosomal translocations involving the NPM1 locus (5q35) were described in hematological malignancies (see reviews) and lung cancer." (PMID 24410879, 2014). "Despite extensive research in hematological malignancies, any roles of NPM1 in solid tumors, its impact on adult tissue homeostasis and the potential for repurposing emerging AML-targeted NPM1 therapies to benefit more patients remain unclear." (PMID 41413654, 2026). "In hematological malignancies, NPM1 belongs to commonly altered genes." (PMID 35621629, 2022). "NPM1/B23 being a major nucleolar protein implicated in hematological malignancies, we hypothesized that a functional association between HBZ and NPM1/B23 could exist." (PMID 36532440, 2022). "Npm1 alterations are cardinal to various hematological malignancies." (PMID 32664415, 2020). "In addition, small insertions and translocations affecting NPM1 gene, encoding NPM, are characteristic of certain hematological disorders." (PMID 26091065, 2015).
hematopoietic cancers (4 papers, 2020 to 2026). "Due to its unique features, NPM1-mutated AML is recognized as a distinct entity in the 2017 WHO classification of hematopoietic neoplasms." (PMID 36280841, 2022). "In hematological tumors, the npm1 gene is frequently combined with other genes giving rise to fusion products that often retain only the NPM1 N-terminal oligomerization domain." (PMID 32664415, 2020). "In hematological tumors with translocations of the NPM1 gene, the contribution of NPM1 stands in its oligomerization properties that facilitate the constitute activation of the kinase partners in the different chimeras." (PMID 32664415, 2020). "This makes NPM1 the most commonly altered gene in hematopoietic cancers." (PMID 40705480, 2025).
genetic diseases (2 papers, 2021). "Another outstanding illustration of the implication of rRNA 2′Ome variations in human genetic disorders has been provided by a recent work focused on the ribosome biogenesis factor nucleophosmin 1 (NPM1)." (PMID 34440717, 2021).
neurodegenerative disease (2 papers, 2018 to 2025). A disorder of the central nervous system characterized by gradual and progressive loss of neural tissue and neurologic function. "One of these was NPM1, a protein implicated in other neurodegenerative diseases and known to interact with misfolded proteins, reducing their mobility and mitigating irreversible aggregation." (PMID 41282153, 2025). "In contrast to several other phase separation-prone proteins associated with neurodegenerative diseases (e.g., FUS22 and hnRNPA120), the aged homotypic NPM1 droplets did not further transition to fibrillar structures after overnight incubation in the presence of 5% PEG." (PMID 30498217, 2018).
gastrointestinal tumors (1 paper, 2022). "However, the relationship between NPM1 and cuproptosis related genes in gastrointestinal tumors has not been studied." (PMID 36188614, 2022).
infectious disease (1 paper, 2015). A disorder directly resulting from the presence and activity of a microbial, viral, or parasitic agent in humans. "Thus, the association of nucleolar protein NPM1 with the viral proteins Rev and US11 may advance our understanding of HIV and HSV pathology and further implies that NPM1 can be exploited as a therapeutic target for infectious diseases." (PMID 26624888, 2015).
metabolism disorders (1 paper, 2025). "Research has found that AML patients with NPM1/polymerin mutations have stronger NAD and purine metabolism disorders, which has identified potential therapeutic targets for the treatment of this subgroup of patients." (PMID 41236698, 2025).
NPM1 also shares sentences with these, for which no sentence is quoted: chronic myeloid leukemia (9 papers); acute megakaryoblastic leukemia (5); acute erythroid leukemia (3); acute monocytic leukemia (3); B-cell lymphoma (3); chronic lymphocytic leukemia (3); inflammatory myofibroblastic tumor (3); psoriasis (3); systemic lupus erythematosus (3); Cirrhosis (2); Down syndrome (2); Fanconi anemia (2); graft versus host disease (2); head and neck squamous cell carcinoma (2); idiopathic pulmonary fibrosis (2); liver disease (2); lymphoid neoplasm (2); thrombocytopaenia (2); thymoma (2); upper tract urothelial carcinoma (2); Wilms tumor (2); adenocarcinoma (1); adenovirus infection (1); Alzheimer disease (1); angioimmunoblastic T-cell lymphoma (1); asthma (1); autism (1); bacterial sepsis (1); bladder urothelial carcinoma (1); blastic plasmacytoid dendritic cell neoplasm (1).
A further 58 diseases each share a sentence with NPM1 in 1 paper.